RETN (resistin)
Diseases named in the same sentence as RETN in open-access papers (continued):
Sharing a sentence is not in itself a finding about the gene and the disease.
heart failure (18 papers, 2011 to 2025). Inability of the heart to pump blood at an adequate rate to meet tissue metabolic requirements. "Elevated circulating resistin levels consistently associate with incident heart failure and adverse outcomes in established patients, independent of traditional cardiovascular risk factors." (PMID 41347124, 2025). "A recent long-term follow-up study revealed elevated serum resistin levels were associated with higher rates of mortality and hospitalization for heart failure." (PMID 21251282, 2011). "However, causal relationships between resistin and human heart failure outcomes remain incompletely resolved." (PMID 41347124, 2025). "Additionally, elevated serum resistin levels have been associated with worse functional status in heart failure patients according to the New York Heart Association (NYHA) classification." (PMID 40283140, 2025). "From a clinical perspective, serum resistin levels have been positively correlated with poor prognosis in patients with heart failure, severity of heart failure, and risk for developing heart failure in elderly subjects, possibly involving the induction of proinflammatory cytokines." (PMID 41515891, 2025). "Clinically, there are few published studies exploring the relationship between serum resistin and heart failure in patients with T2D." (PMID 40283140, 2025). "Clinical data demonstrate divergent relationships between resistin levels and heart failure subtypes." (PMID 41347124, 2025). "Higher resistin level was found in the cardiac dysfunction such as cardiac failure, left ventricular dysfunction and CVD35." (PMID 41315571, 2025). "PRISMA-lite evidence table for resistin’s prognostic value in acute coronary syndromes, heart failure, and atrial fibrillation." (PMID 41347124, 2025). "Collectively, these findings establish the resistin/miR148b-3p/Gadd45α axis as a novel regulatory circuit in heart failure pathogenesis." (PMID 41347124, 2025). "In diabetic heart failure populations, resistin’s predictive accuracy for mortality surpasses that of conventional metabolic markers, highlighting its distinctive role in cardiometabolic risk stratification." (PMID 41347124, 2025). "Due to the limited clinical evidence, the utility of measuring serum resistin levels as an indicator of heart failure progression and prognosis lacks sufficient support to justify its use in routine clinical practice." (PMID 40283140, 2025). "Whole-genome gene expression profiling identified up-regulated heart-failure-related genes such as resistin, adiponectin, and fatty acid synthase, and type 1 and 3 collagens." (PMID 34576047, 2021). "Another previous study also demonstrated that serum levels of resistin, the human homolog of HIMF, are positively correlated with the severity of heart failure and the risk of adverse cardiac events in patients with heart failure." (PMID 34336840, 2021). "Several of the up-regulated genes have a documented relationship to heart failure such as the major fatty-acid-synthesizing enzyme, fatty acid synthase, Fasn, and the heart failure markers adiponectin, Adipoq, and resistin, Retn." (PMID 34576047, 2021). "The increased expression of the heart failure marker resistin correlated with a strongly reduced cardiac ejection fraction of 29.0 ± 2.2 % confirming the development of heart failure upon cystamine treatment." (PMID 21711241, 2011). "Ranolazine also reduced the up-regulated heart failure marker resistin indicating a positive treatment effect on heart function." (PMID 21711241, 2011). "As controls, the heart failure-related protein, resistin (Retn), was specifically up-regulated in aortic-constricted mice with signs of heart failure while ApoE was only expressed in B6 mice." (PMID 21711241, 2011).
heart failure (continued). "This prognostic value persists across heart failure subtypes but demonstrates particular significance in heart failure with reduced ejection fraction, where resistin levels reflect inflammatory burden and myocardial stress independent of traditional biomarkers." (PMID 41347124, 2025). "Combining resistin with indicators of myocardial fibrosis, inflammation, or neurohormonal activation may improve prediction of heart failure hospitalization or arrhythmic events." (PMID 41347124, 2025). "Future research must elucidate resistin’s receptor-mediated signaling pathways, validate its biomarker efficacy across diverse clinical populations, and explore targeted therapeutic interventions for clinical heart failure management." (PMID 41347124, 2025). "Consistently, serum levels of both resistin and RBP4 have previously been reported to be associated with LV diastolic dysfunction and development of heart failure, highlighting the importance of these adipokines in the pathogenesis of heart failure." (PMID 36964443, 2023). "The mechanisms that may explain the ability of circulating resistin concentrations to predict the progression to heart failure and its prognosis are uncertain." (PMID 32000666, 2020). "Although, in-part through an impact on left ventricular mass (LVM), resistin (an adipokine) may contribute to heart failure, whether this is explained by the adverse effects of resistin on aortic stiffness and renal function is unknown." (PMID 32000666, 2020). "As LVM is a well-recognized determinant of the progression to heart failure, the impact of resistin may in-part be explained by effects on LVM." (PMID 32000666, 2020). "Circulating resistin concentrations may therefore be a biomarker of direct rather than indirect actions of resistin on the myocardium which may ultimately predict the progression to heart failure." (PMID 32000666, 2020). "Importantly however, these effects are clearly indexed by circulating resistin concentrations, thus supporting the view that circulating resistin concentrations may be employed as a biomarker of the progression to heart failure." (PMID 32000666, 2020). "Quantitative immunoblotting revealed that cardiac resistin protein levels were significantly higher in mice with signs of heart failure whereas resistin was not different from control mice after 1 month of AAC." (PMID 21711241, 2011).
polycystic ovary syndrome (18 papers, 2010 to 2025). A disorder that manifests as multiple cysts on the ovaries. "Hormone dysregulation (e.g. leptin, ghrelin, resistin, adiponectin), insulin resistance, low levels of sex hormone-binding proteins, high androgen levels, chronic inflammation, and polycystic ovary syndrome (PCOS), are associated with obesity and can lead to ovulatory dysfunction." (PMID 40789178, 2025). "It has been reported that the adiponectin-resistin ratio might be potentially useful in prediction of the future cardiovascular risk in women with the polycystic ovary syndrome." (PMID 21251282, 2011). "Similarly, the effect of supraphysiologic doses of testosterone administration on resistin still remains to be understood though endogenous androgens in Polycystic Ovarian Syndrome (PCOS) have been shown to cause elevated resistin levels after controlling for body mass." (PMID 20706676, 2010). "This meta-analysis was performed to resolve the inconsistencies regarding resistin and follistatin levels in women with polycystic ovary syndrome (PCOS) by pooling the available evidence." (PMID 33740002, 2021). "Thus, it has been suggested that some important differences in polycystic ovaries may facilitate the responsiveness of theca cells to resistin, which may synergise with insulin to increase androgen synthesis." (PMID 31505789, 2019). "For many years, there have been attempts to connect resistin with polycystic ovary syndrome (PCOS), a hormone disorder with disturbed menstrual cycles and cysts on ovaries." (PMID 30131543, 2018). "Moreover, changes of the relative proportion of adiponectin to resistin might play a more important role in hormonal disturbances in polycystic ovary syndrome than the absolute concentrations of these adipokines." (PMID 21251282, 2011).
depression (17 papers, 2013 to 2025). "Nonetheless, they suggest serum resistin as a potential candidate marker for depression because of its robust diagnostic performance and recommend further studies." (PMID 37891727, 2023). "The authors are inconclusive as to whether elevated resistin levels in depression are an effect or cause of the disease." (PMID 37891727, 2023). "Serum resistin might be used to evaluate the risk of developing depression applying the prognostic performance." (PMID 35213631, 2022). "Specifically, it has been suggested that resistin can inhibit dopamine and noradrenaline release in the hypothalamus and can decrease intrasynaptic monoamine levels, which in turn could lead to the predisposition of the development of depression symptoms." (PMID 34579022, 2021). "In support of this idea, recent studies showed that increased resistin serum levels in major depression subjects correlated with high scores for depression (HAM-D)." (PMID 40565847, 2025). "Resistin is an adipocytokine that is generally increased in individuals with depression, especially in those exhibiting an atypical profile of symptoms." (PMID 41375608, 2025). "Our findings reveal that pregnant women experiencing perinatal anxiety and depression exhibited elevated levels of adiponectin, leptin, and resistin levels compared to healthy pregnant subjects." (PMID 40565847, 2025). "Similar to the previously discussed resistin and leptin, elevated serum levels of FetA have been observed in patients with recurrent depressive disorder compared to controls." (PMID 40507778, 2025). "The authors observed increased serum resistin levels in patients with major depressive disorder (MDD) compared to healthy controls and showed a significant correlation of serum resistin with HDRS score." (PMID 37891727, 2023). "In this study, we complement the results with observations from unipolar depression, which indicate different baseline resistin concentrations depending on the subtype of depression." (PMID 37891727, 2023). "The neuropeptides adrenomedullin, insulin-like growth factor 2, prodynorphin, and resistin were identified as mutually expressed in both periodontitis and depression, also playing a role in identifying depression." (PMID 37396968, 2023). "Based on the present study findings, patients with severe depression had a considerable increase in serum resistin levels." (PMID 35213631, 2022). "We propose serum resistin as a potential candidate marker of depression because of its increasing serum levels, connection with illness severity, and firm diagnostic performance." (PMID 35213631, 2022). "Further studies are needed before any conclusions between serum resistin level and the development of depression in high intensity trained RGs can be made." (PMID 34579022, 2021). "As for the relationship between resistin and depression in humans, resistin levels were found to be positively correlated with atypical but not typical depression." (PMID 24109426, 2013). "Conversely, resistin levels are lower in patients receiving antidepressant treatment who have remitted from depression." (PMID 24109426, 2013). "However, results of the studies exploring resistin’s role in the pathogenesis of depression have been inconsistent." (PMID 41375608, 2025). "Parallel research continues into the potential of resistin as a marker for depression." (PMID 40507778, 2025). "Similarly, elevated serum resistin serum levels were detected in adolescents with major depression compared to baseline levels in healthy controls." (PMID 40565847, 2025). "Our findings about the increased circulating levels of both leptin and resistin in pregnant women with anxiety and depression posit that these two important adipocytokines (released from adipocytes or the brain) dysregulate the HPA axis bioactivity, at distinct levels, leading to hypercortisolemia." (PMID 40565847, 2025).
depression (continued). "Some previous studies measured serum resistin levels in depression, but their results were not robust to evaluate the risk of developing depression due to its low prognostic performance." (PMID 35213631, 2022). "Therefore, the therapeutic significance of the relationship between serum resistin and G-CSF levels with depression is still unclear." (PMID 35213631, 2022). "Another study found a higher level of resistin in depression." (PMID 35213631, 2022). "The predictive performance of serum resistin was found fair (0.746) by ROC curve analysis that might be helpful in the management of major depression." (PMID 35213631, 2022). "Furthermore, ROC analysis showed a fairly predictive performance of serum resistin levels in major depression (AUC = 0.746)." (PMID 35213631, 2022). "There have been many studies linking resistin with the development of depression." (PMID 34579022, 2021). "A1AT and resistin have previously been recognized depression-specific serum protein biomarkers." (PMID 28594820, 2017). "In human depression, however, resistin levels positively correlate with salivary cortisol." (PMID 25225489, 2014). "As it currently stands, there are no documented reports exploring the impact of resistin treatment or its loss of function in animal studies of anxiety and depression." (PMID 24109426, 2013). "In line with this, our results posit that stress-inducing anxiety and depression observed in pregnant women could be due to the increased circulating levels of both leptin and resistin, in addition to other immune biomarkers shown to be increased in pregnant subjects with major depression." (PMID 40565847, 2025). "In this context, other studies have demonstrated a positive correlation between blood resistin levels and the occurrence of atypical and melancholic subtypes of major depression, which may indicate a significant role for resistin in the pathogenesis of depression." (PMID 40507778, 2025). "Hence, based on the neuroinflammatory hypothesis of depression, we investigated the concentration of two opposite-acting adipokines (anti-inflammatory adiponectin and proinflammatory resistin) and BDNF in antidepressant-resistant patients undergoing ECT." (PMID 37891727, 2023). "Since the role of this adipokine on anxiety and depression has been scarcely explored, further investigation is needed to determine the possible role of leptin resistance or hyperleptinemia and increased plasma levels of resistin in the increased anxiety-like behavior observed in our MS model." (PMID 28463967, 2017). "Thus, the increase in serum adiponectin levels suggests that its anti-inflammatory activity may counteract or offset the pro-inflammatory processes promoted by leptin, resistin, and other inflammatory immune mediators in pregnant individuals experiencing severe anxiety and depression." (PMID 40565847, 2025). "Therefore, the elevated resistin levels in depression might be the result, not the cause of disease." (PMID 35213631, 2022). "Therefore, we aimed to investigate resistin and G-CSF in MDD patients and controls to explore their role in the pathogenesis and development of depression." (PMID 35213631, 2022). "Thus, we aimed to evaluate the serum resistin and G-CSF of MDD patients in a case-control study to find their relationship with the pathogenesis of depression." (PMID 35213631, 2022). "Another possible explanation is that endocrine factors (such as adipokines including leptin, adiponectin, and resistin, secreted by adipose tissues) might be involved in the effect of BWV on depression." (PMID 34955919, 2021). "However, different studies support the finding that resistin may be a biochemical marker linking an impaired BIP, body composition and the development of depression." (PMID 34579022, 2021). "The present study found elevated serum resistin levels in MDD patients than HCs, but serum G-CSF levels did not alter significantly in depression." (PMID 35213631, 2022).
depression (continued). "Baseline comparisons of adiponectin, resistin, and BDNF concentrations were not significantly different before and after ECT treatment in the entire patient group and subgroups distinguished by depression type, sex, or symptom improvement status." (PMID 37891727, 2023).
Hyperinsulinemia (16 papers, 2007 to 2022). An increased concentration of insulin in the blood. "Recently, however, another study demonstratedthat acute hyperinsulinemia is associated with increased resistin mRNAexpression in human subcutaneous adipose tissue and a similar increase inplasma resistin levels." (PMID 19125180, 2008). "Furthermore, our study found that reduction of resistin with RNA oligo treatment ameliorated hyperinsulinemia and improved impaired GTT." (PMID 25922835, 2015). "Thus, hyperinsulinemia inobese women may happen due to the effects of reduced adiponectin levels andincreased leptin and resistin in circulation." (PMID 28050960, 2016).